DAZ2 (deleted in azoospermia 2)
Description:
RNA-binding protein that plays an essential role in spermatogenesis. May act by binding to the 3'-UTR of mRNAs and regulating their translation.
Synonyms: pDP1678; MGC126442
Tractability: PROTAC: ubiquitination databases record sites on it.
Gene: Protein-coding gene on chromosome Y (23,219,447 to 23,291,356, forward strand). Ensembl gene ENSG00000205944.
Subcellular location: Cytoplasm; Nucleus
Gene Ontology:
Molecular function: protein binding; RNA binding; translation activator activity; mRNA 3'-UTR binding; nucleic acid binding
Biological process: 3'-UTR-mediated mRNA stabilization; positive regulation of translational initiation; single fertilization
Cellular component: cytoplasm; protein-containing complex; nucleus
Homologues: Orthologues: dog DAZL (28% identical), guinea pig DAZL (26% identical), tropical clawed frog dazl (18% identical), zebrafish dazl (13% identical), Caenorhabditis elegans daz-1 (11% identical), Drosophila melanogaster bol (9% identical). Paralogues in human: DAZ4 (85% identical), DAZ3 (66% identical), DAZ1 (62% identical), DAZL (28% identical), BOLL (12% identical).
Diseases named in the same sentence as DAZ2 in open-access papers:
DAZ2 is named in the same sentence as 5 diseases in open-access papers, as found by Europe PMC text mining. Sharing a sentence is not in itself a finding about the gene and the disease. The quoted sentences say what the papers report.
male infertility (2 papers, 2023 to 2024). The inability of the male to effect fertilization of an ovum after a specified period of unprotected intercourse. "DAZ1/DAZ2 deficiency is associated with male reproductive dysfunction and may be a risk factor for male infertility." (PMID 39850494, 2024). "Moreover, we investigate the Y-chromosome genes, DAZ1/DAZ2/DAZ3/DAZ4, of which structural variants have been linked to male infertility, and X-chromosome genes OPN1LW and OPN1MW linked to eye disorders." (PMID 37365340, 2023).
cancer (1 paper, 2022). A tumor composed of atypical neoplastic, often pleomorphic cells that invade other tissues. "MAZ2 performed better than auranofin at its own IC50, and far better than the DAZ2 and TAZ2 structures, containing two and three methoxyls, respectively, which provided evidence of MAZ2′s stronger anti-cancer proliferation efficiency." (PMID 35805931, 2022).
DAZ2 also shares sentences with these, for which no sentence is quoted: Azoospermia (3 papers); Infertility (1); oligospermia (1).